APLN (apelin)
Diseases named in the same sentence as APLN in open-access papers (continued):
Sharing a sentence is not in itself a finding about the gene and the disease.
heart failure (continued). "Basically, as the heart failure aggravates and the congestion increases, the level of NT-proBNP rises and those of apelin-13 lowers." (PMID 34257745, 2021). "During the development of heart failure, the apelin-13 plasmatic level decreases progressively, following its rise in the initial disease phases." (PMID 34257745, 2021). "Based on their generally favorable hemodynamic properties, apelin and apelin-based mimetics are currently in development for the treatment of several cardiovascular disorders, including heart failure, pulmonary hypertension, and ischemia/reperfusion injury." (PMID 34122102, 2021). "Our result was consistent with the previous study, showing that the Apelin played an important role in the early stage of heart failure." (PMID 33342766, 2020). "Some reports suggest that the apelin/APJ system is down-regulated in heart failure and upregulated in left ventricular remodelling." (PMID 31653030, 2019). "Apelin increases cardiac output and lowers blood pressure and peripheral vascular resistance in patients with heart failure." (PMID 29875677, 2018). "The variability in blood serum apelin concentration in patients with cardiac dysfunctions, including arrhythmia and heart failure, cannot be clearly predicted." (PMID 29721104, 2018). "Studies examining olmesartan, an angiotensin II receptor antagonist, as a treatment for hypertension in rats with heart failure, also found, that apelin can be involved in regulation of the Akt/eNOS pathway." (PMID 29875677, 2018). "Reduced circulating apelin levels have been observed in patients with heart failure, coronary artery disease and lone atrial fibrillation as well as in experimental models of isoproterenol-induced cardiomyopathy, I/R heart injury and heart failure." (PMID 30286717, 2018). "In human, it was shown that in early stages of the heart failure, plasma apelin level, parallel to BNP, rises and decreases with the progress of the disease." (PMID 29721104, 2018). "Because it was demonstrated that apelin had a potent inotropic effect in myocardial cells, further in vivo studies were performed to find the effect of apelin in heart failure." (PMID 29302260, 2017). "Diseases that are prominent in the elderly, such as atherosclerosis, hypertension, coronary atherosclerotic heart diseases, heart failure, atrial fibrillation and calcific aortic valve disease (CAVD), have been associated with the apelin–APJ signaling system." (PMID 29302260, 2017). "Further clinical trials are necessary to study the application of apelin in the treatment of cardiac aging, hypertensive cardiomyopathy, and heart failure." (PMID 29302260, 2017). "Reduced apelin expression due to heart failure or angiotensin II administration can be restored by AT1R blockade." (PMID 28293165, 2017). "Both myocardial and plasma apelin levels of heart failure patients decreased simultaneously, suggesting that the heart is a major source of circulating apelin; it plays an essential role in the maintenance of myocardial systolic function." (PMID 29302260, 2017). "In humans, plasma apelin levels decreased in advanced heart failure in most studies, but the studies that focused on the early stages of heart failure demonstrated that apelin levels remained normal or even increased in early stages." (PMID 29302260, 2017). "[Pyr1]apelin-13 is an endogenous vasodilator and inotrope but is downregulated in pulmonary hypertension and heart failure, making the apelin receptor an attractive therapeutic target." (PMID 25712721, 2015). "In the process of heart failure, the expression levels of apelin and the APJ receptor underwent down-regulation in end-stage failing human hearts." (PMID 25993436, 2015). "The cardiovascular profile of the apelin makes it a promising therapeutic target for heart failure and ischemic heart disease." (PMID 25634182, 2015). "A recent study shows that the cardiac apelin is markedly down-regulated in experimental heart failure (HF) animal." (PMID 26342945, 2015).
heart failure (continued). "Recently we showed that apelin gene therapy attenuates heart failure following myocardial infarction." (PMID 29167823, 2015). "Recently, the therapeutic potential of apelin as a reagent for heart failure has been increasingly recognized." (PMID 25639753, 2015). "It is especially interesting that the positive inotropic effect of the peptide is preserved in the failing heart, although the apelin–apelin receptor system is chronically downregulated in heart failure." (PMID 24695532, 2014). "Transplantation of BMCs led to a significant increase in apelin level and improvement of cardiac function in patients with severe heart failure." (PMID 24039710, 2013). "Apelin is down-regulated in patients with heart failure and up-regulated by a favourable left ventricular remodeling." (PMID 20652043, 2010). "Importantly, these beneficial effects of systemic apelin were retained in patients with heart failure and pulmonary arterial hypertension." (PMID 41895070, 2026). "It has been shown that Apelin expression decreases heart failure." (PMID 41154645, 2025). "In another study, in children with heart failure due to congenital heart disease, serum APLN levels showed a negative correlation with HR, and low APLN levels were associated with an unfavorable prognosis in heart failure." (PMID 39857678, 2025). "Given its inodilator effects, apelin is considered a promising candidate to mitigate some adverse effects of β-blockers and could be beneficial for treating heart failure and hypertension, as well as supporting vasopressors during septic shock." (PMID 40141374, 2025). "For instance, Apelin has been shown to upregulate endothelial nitric oxide synthase (eNOS), leading to vasodilation and improved blood flow, which is beneficial in managing hypertension and heart failure." (PMID 39859178, 2025). "Moreover, apelin prevents the development of heart failure in mice fed a high-fat diet and subjected to pressure overload via aortic banding." (PMID 41515891, 2025). "Furthermore, in a pressure-overload-induced heart failure model, apelin-knockout mice also developed severe impairment in heart contractility." (PMID 41155377, 2025). "In clinical conditions such as heart failure and atherosclerosis, the gene expression and circulating levels of Apelin may decrease or stay unchanged." (PMID 41154645, 2025). "Apelin demonstrates superior binding strengths with key receptors involved in cardiovascular health, alongside its ability to modulate multiple signaling pathways, which are crucial for managing hypertension and heart failure." (PMID 39859178, 2025). "Similarly, apelin-13 has been shown to positively impact cardiac function in rats with heart failure by ameliorating cardiac dysfunction, alleviating compromised hemodynamics, and decreasing fibrosis and oxidative stress." (PMID 39335642, 2024). "Apelin, which is a particularly potent inotropic agent, induces endothelium-mediated vasodilatation; indicatively, chronic apelin administration to heart failure patients, which are characterized by low apelin levels, was observed to boost cardiac performance and output." (PMID 39457235, 2024). "Apelin and APJ are also expressed in vascular smooth muscle cells, endothelial cells, and myocardial cells, and low apelin levels are reported in patients with heart failure, suggesting that they are involved in the myocardial response to infarction and ischemia." (PMID 38672227, 2024). "The combined effect of increased contractility with reduced ventricular preload and afterload implicates APLN as a promising target for treatment of heart failure, along with the observations that tissue levels of APLN are increased in early stages of heart failure but decrease in advanced disease." (PMID 37965580, 2023). "Apelin has been found to be an essential biomarker for heart failure." (PMID 37510916, 2023).
heart failure (continued). "Overall, a combination of inotropy and vasodilatation has been shown to improve haemodynamics in acute heart failure, and targeting the apelin system in heart failure could therefore offer benefit over and above that from currently available treatments." (PMID 37956047, 2023). "In the overexpression of natriuretic peptides in heart failure, the level of apelin is reduced." (PMID 37779742, 2023). "The mechanism that leads to reduction of apelin in patients with OHCM may be similar to that in heart failure with reduced LVEF, or due to its unique pathological changes of myocardium." (PMID 35783816, 2022). "A variety of hypotheses have been proposed to explain why apelin levels are reduced in heart failure." (PMID 35783816, 2022). "In addition to nitric oxide, endothelium is known to produce other factors that support cardiac function and alleviate progression of heart failure, including neuregulins and apelin." (PMID 36269647, 2022). "Recent studies have found that apelin-mediated signalling is connected to heart failure and IHD." (PMID 35663309, 2022). "Considering the positive inotropic and vasodilative effects of apelin, the down-regulation may be an upstream event of heart failure." (PMID 35783816, 2022). "Besides, there were marginally more patients suffering from heart failure of NYHA functional class III or IV in lower apelin group (33 vs. 15%, p = 0.053)." (PMID 35783816, 2022). "Furthermore, plasma apelin levels are increased by glucose administration and in certain conditions such as heart failure with chronic systemic hypoxia, and decreased by osmotic stimuli." (PMID 34421653, 2021). "Importantly, administration of [Pyr1]-Apelin-13 (Ape13), the predominant Apelin fragment detected in human plasma and heart, was found to exert beneficial effects in heart failure patients." (PMID 34385922, 2021). "The serum values of ACE2 and apelin-13 correlate with the unfavourable outcome in patients with reduced ejection fraction heart failure and may be useful biomarkers in determining the prognosis of these patients." (PMID 34257745, 2021). "In this aspect, the apelin–APJ system is attractive because it appears to be downregulated in heart failure, and stimulation of this pathway may have additive or even synergistic efficacy to current therapy by targeting complementary but separate pathways." (PMID 32231588, 2020). "In particular, apelin plays an important role in the occurrence and development of heart failure." (PMID 32686917, 2020). "Indeed, intravenous administration of [Pyr1] apelin-13, an active fragment of apelin, in heart failure patients showed efficacy with peripheral and coronary vasodilatation and increases in cardiac output." (PMID 32231588, 2020). "As observed previously in ventricles of patients with heart failure, we found reduced apelin levels in right atrial homogenates from patients with AF, suggesting that decreased apelin-APJ signaling may contribute to the maintenance and pathophysiology of AF." (PMID 32879139, 2020). "The beneficial effects of apelin in heart failure are well characterised." (PMID 31882594, 2019). "Furthermore, our result provided novel morphological evidences concerning the cardiovascular protective potential of apelin on heart failure." (PMID 31316680, 2019). "Our data may therefore suggest that an additional benefit of neprilysin inhibitors in heart failure is to reduce apelin inactivation resulting in beneficial vasodilation, increased contractility and cardiac output." (PMID 31882594, 2019). "The use of apelin as a biomarker in human heart failure has been challenging." (PMID 31653030, 2019). "Thus, cardiac hypertrophy and fibrosis are key features of heart failure, and apelin’s inotropic and protective roles in the heart are attractive as a potential therapeutic candidate for treating heart failure." (PMID 30634441, 2019).
heart failure (continued). "In heart failure, the level of apelin rises in the initial stage of the disease parallel with BNP and decreases in the advanced stage—those observations, in our opinion, might also be applied to patients with AF." (PMID 29721104, 2018). "This may have potential clinical applications as apelin has been introduced as a potential therapeutic agent in heart failure and opioids are being currently used in the treatment of myocardial infarction." (PMID 30627376, 2018). "The decrease in receptor density in heart failure may limit the positive inotropic actions of apelin, resulting in an initial compensatory mechanism by increasing apelin to improve myocardial contractility." (PMID 29302260, 2017). "Importantly, in healthy volunteers and heart failure patients, the major effect of apelin infused into the forearm in vivo was nitric oxide dependent arterial dilatation." (PMID 28293165, 2017). "Data suggest that activating the apelin pathway may be valuable in conditions, such as heart failure and pulmonary arterial hypertension." (PMID 25712721, 2015). "The pathway of apelin and its apelin receptor (APJ) was implicated in the pathogenesis of heart failure in animal models, but a similar role in humans is unknown." (PMID 25993436, 2015). "Future comprehensive genetic analysis by genotyping and analyzing more SNPs in the APLNR gene and other genes in the apelin/APJ pathway as well as haplotype analysis may further define the role of the apelin/APJ pathway in the pathology of heart failure." (PMID 25993436, 2015). "The apelin system is downregulated in pulmonary arterial hypertension and heart failure; therefore." (PMID 25712721, 2015). "The peptide offers numerous potential advantages, particularly for heart failure therapy: apelin is a potent vasodilator of arteries and veins thereby reducing pre- and afterload, antagonizes the renin-angiotensin system, has anti-fibrotic effects, and enhances the force of cardiac contractions." (PMID 24695532, 2014). "Our data suggest that modification of BMCs with apelin could use as a novel cell-based therapy for the treatment of patients with myocardial ischemia and heart failure." (PMID 24039710, 2013). "In addition to the possibility of application of apelin as a heart failure (HF) biomarker, apelin also has direct biological effects including vasodilatory and inotropic effects." (PMID 22655211, 2012). "Apelin has emerged as a promising peptide biomarker of heart failure." (PMID 22655211, 2012). "Apelin is mainly considered a vascular hormone: actually, it induces an endothelium-dependent vasodilation, exerts inotropic effects, and plays a protective role in the pathogenesis of heart failure by modulating the harmful effects of Ang II." (PMID 20652043, 2010). "In fact, apelin signaling may augment inhibition of the renin-angiotensin system, which is known to exacerbate heart failure when left unchecked." (PMID 18648539, 2008). "Apelin has inotropic effects on cardiac contractility and has been shown to decrease systemic vascular resistance, and is therefore likely beneficial during heart failure." (PMID 18648539, 2008). "The apelin inotropic effect may play a protective role in heart failure conditions." (PMID 40943120, 2025). "The results with agonists demonstrate apelin is limited to two principal actions in humans in health and disease: modest vasodilatation within the first hour of systemic infusion and a beneficial increase in cardiac output that is maintained for up to six hours in patients with heart failure." (PMID 38803685, 2024). "The present study aimed to determine whether apelin-13 could attenuate cardiac fibrosis via inhibiting the phosphatidylinositol 3-kinase/protein kinase B (PI3K/Akt) pathway to inhibit reactive oxygen species in heart failure (HF) rats." (PMID 32207519, 2020). "Thus, apelin is a potential innovative treatment for heart failure." (PMID 31316680, 2019).
heart failure (continued). "Indeed, the blood pressure-lowering action of apelin is well documented in several animal models and in patients with heart failure and apelin is known to act on vascular smooth muscle cells, inducing either vasodilatation or vasoconstriction via different pathways." (PMID 31505789, 2019). "Indeed, combined gene therapy has recently shown significant promise in the treatment of animal models of heart failure, with combined transfer of apelin, fibroblast growth factor-2, and SERCA2a demonstrating increased gene expression in ischemic heart failure model." (PMID 29621141, 2018). "Based on theabove findings, it might be concluded that up regulationof Apelin in cardiac muscle of diabetic rats may improvethe function of cardiac muscle in this condition and mayattenuate the pathophysiological complications in patientswith heart failure." (PMID 29845798, 2018). "Thus, apelin could be used as a factor that has both a cardiotonic and afterload lowering effect in heart failure patients." (PMID 29302260, 2017). "Thus, up-regulation of APJ and apelin in the early stage of heart failure after ischemia may confer a potent protective effect on cardiac contractility and modulate systemic vascular resistance to antagonize the injury of ischemia or hypoxia." (PMID 25993436, 2015). "Clinical studies are already underway to explore the therapeutic use of ELA and apelin in both acute and chronic heart failure—for instance, ELA is being proposed as a preventive early biomarker and a novel cardiotropic agent for heart failure treatment." (PMID 41155377, 2025). "There is evidence that the concentration of apelin decreases with age, which along with a decreased level of the angiotensin 2 conversion enzyme (ACE2) results in a deepening heart failure." (PMID 40943120, 2025). "Indeed, treatment of mouse cardiac fibroblasts with apelin reduced fibroblast activation and collagen production, which was mediated by a reduction in sphingosine kinase 1; this was similarly observed in an in vivo model of heart failure produced by aortic banding." (PMID 41515891, 2025). "In recent years, a growing body of evidence has highlighted the potential of apelin and ELA as therapeutic targets for the treatment of CV diseases, such as hypertension, ischaemic heart disease, and heart failure." (PMID 37242650, 2023). "In this review, we explore the recent insights regarding the potential of apelin/ELA-APJ signal activation as therapeutic strategy in hypertension, MI, and heart failure." (PMID 37242650, 2023). "In patients with a low ejection fraction heart failure, serum activity of ACE2 has elevated values, and apelin appears to have a positive regulatory role in ACE2 in these patients." (PMID 34257745, 2021). "Furthermore, apelin counteracts the effects of angiotensin-II signalling, which is negatively regulated by ACE2, suggesting that targeting ACE2 and apelin could be a potentially novel therapeutic strategy for treatment of lung injury related pathologies and heart failure." (PMID 31882594, 2019). "Studies showed that in an isoproterenol-induced model of heart failure, LVSD was partially rescued by co-administration of apelin." (PMID 25993436, 2015). "To date, apelin has been regard as a potential marker of coronary artery stenosis and atherosclerotic plaque stability in ACS patients and heart failure patients." (PMID 26342945, 2015). "Emerging data suggest that the cardiovascular system is the main target of apelin, which exerts an overall neuroprotective role, and is a positive regulator of angiotensin-converting enzyme 2 (ACE2) in heart failure." (PMID 25164432, 2014). "It is important to note that in healthy heart tissue, apelin is not present, but in patients with heart failure, both apelin and the apelin receptor have been found." (PMID 40943120, 2025).